TPM1 (tropomyosin 1)
Description:
Binds to actin filaments in muscle and non-muscle cells. Plays a central role, in association with the troponin complex, in the calcium dependent regulation of vertebrate striated muscle contraction. Smooth muscle contraction is regulated by interaction with caldesmon. In non-muscle cells is implicated in stabilizing cytoskeleton actin filaments.
Synonyms: C15orf13; TMSA; CMD1Y; CMH3; HEL-S-265; HTM-alpha; LVNC9
Tractability: Small molecule: a structure with a bound ligand is known. PROTAC: ubiquitination databases record sites on it; its protein half-life has been measured.
Gene: Protein-coding gene on chromosome 15 (63,042,481 to 63,071,915, forward strand). Ensembl gene ENSG00000140416.
Subcellular location: Cytoplasm, cytoskeleton
Subcellular location (Human Protein Atlas): Actin filaments; Cytosol
Pathways (Reactome):
Muscle contraction: Smooth Muscle Contraction; Striated Muscle Contraction
Gene Ontology:
Molecular function: cytoskeletal protein binding; protein binding; actin binding; actin filament binding; identical protein binding; protein heterodimerization activity; protein homodimerization activity; structural constituent of cytoskeleton; structural constituent of muscle
Biological process: cardiac muscle contraction; cellular response to reactive oxygen species; negative regulation of vascular associated smooth muscle cell migration; negative regulation of vascular associated smooth muscle cell proliferation; regulation of cell shape; sarcomere organization; ventricular cardiac muscle tissue morphogenesis; actin filament organization; cytoskeleton organization; muscle filament sliding; negative regulation of cell migration; positive regulation of cell adhesion; positive regulation of heart rate by epinephrine; positive regulation of stress fiber assembly; regulation of heart contraction; regulation of muscle contraction; ruffle organization; wound healing
Cellular component: bleb; ruffle membrane; stress fiber; actin filament; cytoskeleton; cytosol; muscle thin filament tropomyosin; sarcomere
Genetic constraint (gnomAD): Loss-of-function variants: 23 observed, 43.06 expected, observed/expected ratio (o/e) 0.53, 90% interval 0.38 to 0.76. The upper end of that interval is the gene's LOEUF score, 0.76, which puts it in group 3 of 6, group 1 being the genes least tolerant of losing a copy. Missense variants: 158 observed, 364.23 expected, observed/expected ratio (o/e) 0.43, 90% interval 0.38 to 0.5. Synonymous variants: 136 observed, 135.5 expected, observed/expected ratio (o/e) 1, 90% interval 0.87 to 1.16.
Gene-disease validity (ClinGen):
ClinGen rates the evidence that TPM1 causes each of these diseases.
hypertrophic cardiomyopathy (autosomal dominant): Definitive. A condition in which the myocardium is hypertrophied without an obvious cause.
dilated cardiomyopathy 1Y (autosomal dominant): Moderate.
arrhythmogenic right ventricular cardiomyopathy (autosomal dominant): No Known Disease Relationship.
Homologues: Orthologues: zebrafish tpm1 (93% identical), zebrafish tpma (92% identical), chimpanzee TPM1 (92% identical), mouse Tpm1 (92% identical), rat Tpm1 (92% identical), dog TPM1 (91% identical), tropical clawed frog tpm1 (87% identical), rabbit TPM1 (82% identical), pig TPM1 (79% identical), guinea pig TPM1 (78% identical), macaque TPM1 (73% identical), Drosophila melanogaster Tm1 (56% identical), and 2 more. Paralogues in human: TPM3 (91% identical), TPM2 (86% identical), TPM4 (63% identical).
Diseases named in the same sentence as TPM1 in open-access papers:
TPM1 is named in the same sentence as 158 diseases in open-access papers, as found by Europe PMC text mining. Sharing a sentence is not in itself a finding about the gene and the disease. The quoted sentences say what the papers report.
breast carcinoma (38 papers, 2009 to 2025). "Genes identified included novel genes such as HPGD, FASN and KRT81, as well as SCIN and TPM1 which have already been confirmed in acquired drug resistance mechanisms associated with HER2-positive breast cancer." (PMID 40946111, 2025). "It suppresses malignancy in glioma by regulating TPM1 splicing, linked to various cancer types, including breast cancer, lung cancer, and prostate cancer." (PMID 37924098, 2023). "In breast cancer cells, loss of TPM1 conferred anoikis resistance and overexpression of TPM1 suppressed anchorage-independent growth." (PMID 23213280, 2012). "Moreover, TNC expression appears to be linked to lung metastasis in breast cancer and leads to a downregulation of tropomyosin-1 and the Wnt inhibitor Dickkopf 1, what in turn results in the destabilization of actin stress fibers and an enhanced Wnt signaling." (PMID 30380741, 2018). "Because loss of TPM1 expression in breast cancer cells abolishes anoikis, and the forced expression of the KSHV protein vFLIP inhibits anoikis, we hypothesized that KSHV-infected cells are partially resistant to this particular type of cell death." (PMID 26263384, 2015). "Moreover, as TLRs ligands, LPS was reported to increase breast cancer metastasis in vitro and in vivo, and acquiring of high metastatic potential upon the TLR4-elicited activation of NF-κB in breast cancer cells was associated with integrin αvβ3, TPM1 and maspin." (PMID 33363472, 2020). "As a member of TPM family, TPM1 has been regarded as a tumor suppressor gene in a series of tumors, e.g., bladder cancer, lung cancer, breast cancer, colorectal cancer, gastric cancer, and hepatocellular carcinoma." (PMID 37854295, 2023). "In Tpm1.1-transfected MDA-MB-231 cells (human breast cancer cell line) which normally lack endogenous Tpm1, DAPK1 overlapped with Tpm1.1 predominantly at the cell edge, where rigidity sensing activity typically occurs." (PMID 35927990, 2022). "Because anoikis is inhibited by TPM1 downregulation in breast cancer cells, and also by KSHV-induced expression of vFLIP,323 it is proposed that KSHV-infected cells show partial resistance to anoikis cell death." (PMID 33898103, 2021). "TPM1 contains a miRNA-21 binding site and acts as a miR-21-mediated tumor suppressor gene in breast cancer." (PMID 33193757, 2020). "Tropomyosin 1 (TPM1) was confirmed to be a target gene of miR-21 in breast cancer cells by fluorescence reporter gene analysis and western blot." (PMID 32637580, 2020). "Consistent with results from breast cancer models, down-regulation of the TPM1 isoform TM3 by miR-K2 or by a siRNA enhances viability of cells that have become detached from a growth surface." (PMID 26263384, 2015). "Other instances of miR-21 targeted signaling pathways included TPM1 in breast cancer MCF-7 cells, and Matrix Metalloproteinase regulators in glioma cells." (PMID 24112539, 2013). "Another study also confirmed that miR-21 targets the tumor suppressor tropomyosin 1 (TPM1), and overexpressing TPM1 in breast cancer cells resulted in suppressed clonogenic potential." (PMID 23202960, 2012). "Another potential gene targeted by miR-21 in breast cancer was Tropomyosin 1 (TPM1), which play an important role in antioncogenic function including binding microfilaments and regulating cytoskeleton miRNAs." (PMID 19644558, 2009). "The involvement of some of the genes affecting cancer cell death–Adm, Cflar, Cyr61, Ddit4, Itgb1, Mapk1, Mapk8, Tgfβ2, Tpm1, Vegfα and Wasf1, was demonstrated in breast cancer cell lines." (PMID 19450255, 2009). "In previous studies, ARHGAP11A was found to promote the development of basal breast cancer, colon cancer, hepatoma, and gastric cancer by accelerating cell transition from the G1 to S phase, inactivating Rac1B or regulating the TPM1-mediated actin filament stability." (PMID 37175461, 2023). "Bharadwaj and Prasad first reported the level of TPM1 expression declined in breast cancer." (PMID 34850589, 2022).
breast carcinoma (continued). "Ingenuity pathway analysis (IPA) revealed that the upregulated proteins hornerin (HRNR), tropomyosin alpha-1 chain (TPM1), annexin A (ANXA2), and protein-disulfide isomerase (PDI) were associated with breast or gynecological cancer, breast carcinoma, and inflammation of organ." (PMID 34771120, 2021). "The role of TPM1 in miR-21-mediated breast cancer cell motility and invasion has been reported." (PMID 33193757, 2020). "The tumor suppressing function of TPM1 was demonstrated in a breast cancer model." (PMID 28182650, 2017). "Another study demonstrated 5-aza-dC treatment induced up-regulation of TPM2 (encoding Tm1), but not TPM1, in metastatic breast cancer cells, while TPM1 and TPM2 were both up-regulated in demethylated fibrosarcoma cells." (PMID 26475688, 2015). "Independently, tropomyosin-1 was reported to regulate anoikis in breast cancer cells." (PMID 25349534, 2014). "In addition, miR-21 has also been found to be upregulated in breast cancers that are associated with low expression of programmed cell death 4 (PDCD4) and tropomyosin 1 (TPM1)." (PMID 24281118, 2010). "TPM1 and TPM4, which were downregulated in comparison with both controls, are known to be differentially abundant in breast cancer epithelial vs. normal breast tissues." (PMID 34771120, 2021). "Studies have demonstrated that miR-21 plays an oncogene function in breast cancer by targeting tumor suppressor genes which include programmed cell death 4 (PDCD4), tropomyosin 1 (TPM1), and phosphatase and tensin homolog (PTEN)." (PMID 34552867, 2021). "Silencing of the miR-21 target gene PTEN promotes invasion and migration in ovarian epithelial carcinomas, and the repression of the miR-21 target genes TPM1, PDCD4, and maspin can enhance invasion and metastasis in breast cancer." (PMID 33193757, 2020). "mir21, as a master regulator of the metastatic processes was found to stimulate cell invasion by targeting tumor suppressors TPM1, PDCD4 and SERPINB5 in breast cancer or colon cancer." (PMID 24069219, 2013). "As miR-21-5p overexpression increased cell growth, invasion and migration, and reduced apoptosis, through downregulation of several tumor suppressor genes such as PTEN, TPM1, and PDCD4, miR-21-5p is likely to be a true prognostic factor for breast cancer and other cancers." (PMID 27409424, 2016). "Moreover, it was verified that TPM1 plays an essential role by inhibiting migration in colorectal carcinoma, breast cancer, gliomagenesis and renal carcinoma, but none of these cancers were mentioned in Jinsong Li’s study." (PMID 28182650, 2017).
cardiomyopathy (28 papers, 2008 to 2026). A disease of the heart muscle or myocardium proper. "Missense mutations in the TPM1 gene associated with cardiomyopathies have been studied in the sarcomeric isoform Tpm1.1." (PMID 42280091, 2026). "Many other sarcomeric proteins have been previously linked to cardiomyopathies, including TPM1, an interacting partner of TMOD1." (PMID 38168645, 2024). "Assessments vary widely regarding the frequency of TPM1-associated cardiomyopathy cases, though it is likely low with most estimating TPM1 is responsible for about 3–5% of all HCM cases." (PMID 36158814, 2022). "The cardiomyopathy mutations I92T and V95A were located in the a and d positions of the heptad repeat, in the core of Tpm1.164–154." (PMID 34834072, 2021). "Further, a number of genes encoding structural proteins have been associated with both cardiomyopathies and CHDs in the same individuals, such as TPM1, MYH7 and alpha cardiac actin." (PMID 28359939, 2017). "Point mutations in alpha tropomyosin (TPM1) are associated with inherited cardiomyopathies, most notably hypertrophic cardiomyopathy (HCM) and dilated cardiomyopathy (DCM)." (PMID 27833562, 2016). "Nonetheless, caution should be applied when using this logic, as pathogenic variants can exhibit significant variable expressivity (e.g., some pathogenic TPM1 missense variants are associated with extreme intrafamilial variation in both age at onset and severity of cardiomyopathy)." (PMID 37443332, 2023). "Besides the hub genes of MYBPC3, MYH7, and DSP, these subnetworks also include several genes that have been implicated in cardiomyopathy, such as TPM1, ACTC1, DES, TCAP, JUP, and DSG2." (PMID 32344918, 2020). "Downregulated proteins in the aged group (TUBGCP2 and SLC25A11) were enriched in cytoskeletal dynamics and cardiomyopathy pathways, whereas upregulated proteins (ATP6V0D2 and TPM1) associated with oxidative stress and neurodegenerative disorders." (PMID 40662159, 2025). "These genes are associated with cardiomyopathy, familial hypertrophic, 4, or CMH4 (OMIM #115197) for MYBPC3, CMH1 (OMIM #192600) for MYH7, CMH3 (OMIM #115196) for TPM1, CMH2 (OMIM #115195) for TNNT2, and CMH7 (OMIM #613690) for TNNI3." (PMID 36555486, 2022). "Data on de novo mutations in non-syndromic cardiomyopathies are limited and include variants in ACTC, MYH7, TNNI3, TNNT2, and TPM1." (PMID 32013205, 2020). "In 8/12 probands (66.7%), we found likely causative variants in known cardiomyopathy genes (TTN, DSP, SCN5A, TNNC1, TPM1, CRYAB, and MYH7), which were confirmed as de novo (six DCM, one HCM, and one RCM case)." (PMID 32013205, 2020). "In 8 (66.7%), we found de novo variants in known cardiomyopathy genes (TTN, DSP, SCN5A, TNNC1, TPM1, CRYAB, MYH7)." (PMID 32013205, 2020). "Several proteins involved in heart failure were downregulated, which were found with the terms “Dilated cardiomyopathy” and “Cardiac muscle contraction”, such as TPM1 (Tropomyosin 1), TNNT2 (Troponin T2), ACTC1 (Actin, alpha, cardiac muscle 1)." (PMID 32165613, 2020). "Therefore, the objectives of this study were to establish the functional association between TPM1-p.Glu181Lys and the RCM phenotype and to elucidate its molecular mechanisms in inducing cardiomyopathy." (PMID 41568329, 2025). "Prominently downregulated proteins (TUBGCP2, NPR2, MT-ATP6, SLC25A11, and so on) were enriched in cytoskeletal dynamics and cardiomyopathy pathways, while upregulated proteins (ATP6V0D2, HNRNPA1, TPM1, and so on) associated with oxidative stress responses and neurodegenerative disorders (AD and PD)." (PMID 40662159, 2025). "In April 2024, the ClinGen Cardiomyopathy Variant Curation Expert Panel (VCEP) adapted the ACMG/AMP criteria for eight of the sarcomeric genes (MYH7, MYBPC3, TNNI3, TNNT2, TPM1, ACTC1, MYL2, and MYL3), providing a refined framework for variant interpretation in these genes." (PMID 41357762, 2025).
cardiomyopathy (continued). "The cardiomyopathy-causing mutations E40K and E54K are located in exon 2b of the TPM1 gene and may be expressed in non-muscle cytoplasmic Tpm isoforms, including Tpm1.7, which is associated with early tissue development." (PMID 42280091, 2026). "Therefore, mutations in the TPM1 gene exclusively cause cardiomyopathy without associated clinical myopathy—despite its expression in skeletal muscle—likely mediated by C-terminal alternative splicing of tissue-specific isoforms." (PMID 41568329, 2025). "Interestingly, mutations in TPM1 result only in cardiomyopathy, with no associated clinical myopathy despite also coding for skeletal muscle protein, possibly due to alternative splicing of the C-terminus." (PMID 36158814, 2022). "A few lncRNAs are located in the introns of cardiomyopathy-related genes (e.g., TTN, ACTC1, TPM1, JPH2, ANKRD1, DTNA, TMPO, and FHL2) or physically close to these genes." (PMID 32344918, 2020). "Therefore, it was speculated that TPM1, MYL2 and MYH11 could be the targets of obesity-induced cardiomyopathy, thus providing a theoretical basis for future drug development." (PMID 33785854, 2021). "Secondly, the in-depth mechanism of TPM1, MYL2 and MYH11 protein changes in obese cardiomyopathy has not been studied." (PMID 33785854, 2021).
hypertrophic cardiomyopathy (28 papers, 2006 to 2026). "Tropomyosin 1 plays a role in calcium mediated muscle contraction and associates to several heart diseases, including hypertrophic cardiomyopathy and CAD." (PMID 39187864, 2024). "Support for the importance of TPMs to muscle contraction is also derived from studies of cardiac muscle in which TPM1 mutations have been associated with systolic hypercontractility in hypertrophic obstructive cardiomyopathy." (PMID 33661765, 2021). "Defects in TPM1 are the cause of familial hypertrophic cardiomyopathy 3 (CMH3) with a high risk of cardiac failure and sudden cardiac death." (PMID 18793429, 2008). "Heterozygous point mutations in TPM1, account for <5% cases of familial hypertrophic cardiomyopathy." (PMID 16472378, 2006). "Mutations in TPM1 have also been linked with familial hypertrophic cardiomyopathy." (PMID 27218255, 2016). "Notably, while mutations in TPM1 (encoding the α-tropomyosin chain) have been well-established in hypertrophic cardiomyopathy (HCM) and dilated cardiomyopathy (DCM), definitive pathogenic evidence linking it to RCM remains exceptionally rare, and the specific molecular mechanisms are unclear." (PMID 41568329, 2025). "Pathogenic TPM1 mutations account for 1%–2% of dilated cardiomyopathy (DCM) cases, 5% of hypertrophic cardiomyopathy (HCM) cases, and 3% of restrictive cardiomyopathy (RCM) cases, based on limited cohort evidence." (PMID 41568329, 2025). "In the cases of dilated cardiomyopathy, cardiac muscle contraction, and hypertrophic cardiomyopathy (B), seven downregulated proteins were enriched, including Myl2, Myl3, Myh7, Atp2a1, Tpm1, Tpm2, and Ttn." (PMID 39861068, 2024). "Pathogenic variants in genes such as MYH7, TPM1, and TNNI3 that encode parts of the cardiac sarcomere cause muscle diseases that affect the heart, such as dilated cardiomyopathy and hypertrophic cardiomyopathy." (PMID 37457373, 2023). "In our dataset, MYOZ2 (myoz2a), TPM1 (tpm1) and TNNC1 (tnnc1a) have been identified which are previously reported to be linked with diverse forms of dilated and hypertrophic cardiomyopathy." (PMID 26815362, 2016). "For example, various TPM1 and TPM2 mutations have been implicated in hypertrophic cardiomyopathy (HCM) including familial hypertrophic cardiomyopathy (FHC) in humans." (PMID 27703814, 2016). "Lev-11 is orthologous to human tropomyosin 1 (TPM1), in which mutations lead to familial hypertrophic cardiomyopathy." (PMID 20858264, 2010). "TPM1 is linked to several cardiac muscle phenotypes such as dilated cardiomyopathy, hypertrophic cardiomyopathy, and left ventricular noncompaction in humans." (PMID 40944391, 2026). "Interestingly, while Tpm1 is one of the main hypertrophic cardiomyopathy genes, Tpm4 is known for its inhibitory effect on actin polymerization." (PMID 36013195, 2022). "Additionally, two VUS in the genes TPM1 (related to hypertrophic cardiomyopathy) and LDB3 (related to hypertrophic cardiomyopathy and dilated cardiomyopathy) were detected in the genetic testing." (PMID 33919104, 2021). "The results showed that genes (DES, MYH6, MYL2, MYL3, TPM1, TPM3, TPM4, and TTN) in MCODE 2 were significantly involved in dilated cardiomyopathy and hypertrophic cardiomyopathy (HCM)." (PMID 35645614, 2022). "KEGG analysis revealed that TPM1 and MYL2 were involved in the hypertrophic cardiomyopathy (HCM) pathway." (PMID 33785854, 2021). "The ‘Hypertrophic cardiomyopathy’ pathway was also significantly enriched, including genes such as ATPase sarcoplasmic/endoplasmic reticulum Ca2+ transporting 2 (ATP2A2) and others already identified in the PPI network (e.g., TPM1 and ACTC1)." (PMID 40559872, 2025). "Of these proteins, MYH7, TPM1 and MYOZ2 are known to be important in hypertrophic cardiomyopathy, and may play a similar role in HFpEF." (PMID 36093146, 2022).